EUDAL (EGFR ubiquitination and degradation associated lncRNA)
Gene: Long non-coding RNA gene on chromosome 1 (230,280,312 to 230,281,893, reverse strand). Ensembl gene ENSG00000224407.
Diseases named in the same sentence as EUDAL in open-access papers:
EUDAL is named in the same sentence as 1 disease in open-access papers, as found by Europe PMC text mining. Sharing a sentence is not in itself a finding about the gene and the disease. The quoted sentences say what the papers report.
tumor (1 paper, 2025). "High expression of EUDAL facilitates sustained phosphorylation of EGFR in hypoxic tumor cells and subsequently activates downstream STAT3/BNIP3 signaling, which leads to autophagy-related drug resistance." (PMID 40940319, 2025). "The binding of EUDAL to EGFR prevents its ubiquitination and degradation, facilitates its sustained phosphorylation, and subsequently activates downstream STAT3 signaling, which leads to autophagy-related drug resistance in tumor cells." (PMID 40940319, 2025).